SNORD116-21 (small nucleolar RNA, C/D box 116-21)
Synonyms: HBII-85-21
Gene: Small nucleolar RNA gene on chromosome 15 (25,088,804 to 25,088,895, forward strand). Ensembl gene ENSG00000277785.
Gene Ontology:
Biological process: RNA processing
Cellular component: nucleolus
Homologues: Orthologues: macaque SNORD116 (99% identical), guinea pig SNORD116 (89% identical), guinea pig SNORD116 (87% identical). Paralogues in human: SNORD116-17 (99% identical), SNORD116-19 (99% identical), SNORD116-14 (98% identical), SNORD116-15 (98% identical), SNORD116-18 (98% identical), SNORD116-20 (98% identical), SNORD116-22 (98% identical), SNORD116-16 (96% identical), SNORD116-12 (92% identical), SNORD116-23 (92% identical), SNORD116-24 (92% identical), SNORD116-2 (89% identical), and 20 more.